PTH (parathyroid hormone)
Diseases named in the same sentence as PTH in open-access papers (continued):
Sharing a sentence is not in itself a finding about the gene and the disease.
secondary hyperparathyroidism (continued). "We recommend checking for biochemical and radiographic features of secondary hyperparathyroidism at diagnosis of ML II by checking levels of PTH, Ca, P, ALP, Vitamin D and by performing skeletal survey." (PMID 35268460, 2022). "CTX-1 and parathyroid hormone levels, and the prevalence of secondary hyperparathyroidism increased more after distal RYGB." (PMID 34791048, 2021). "PTH has been the primary indicator for treatment adequacy in managing secondary hyperparathyroidism in CKD." (PMID 33022030, 2021). "Hypocalcemia, secondary to decreased calcitriol-induced calcium intestinal absorption, calcium-phosphate precipitation in extra-skeletal tissues and skeletal resistance to PTH action, further enhances and sustains secondary hyperparathyroidism." (PMID 34422722, 2021). "Secondary hyperparathyroidism (sHPT) was characterized by persistently elevated serum PTH levels and parathyroid hyperplasia." (PMID 33991027, 2021). "When renal function is impaired, excessive phosphate increases PTH secretion and decreases the active form of vitamin D, which in turn induces secondary hyperparathyroidism." (PMID 34069053, 2021). "Conclusively, a positive loop between leptin and PTH is probably the case in primary hyperparathyroidism, whereas PTH seems to inhibit leptin expression in severe secondary hyperparathyroidism." (PMID 34422722, 2021). "Patients with secondary hyperparathyroidism are also known to have increased levels of PTH in response to low levels of serum 25(OH)D." (PMID 34207469, 2021). "Secondary hyperparathyroidism (SHPT) is defined as an appropriate increase in parathyroid hormone (PTH) secretion, driven by either reduced serum calcium or increased phosphate concentrations, due to an underlying condition." (PMID 34371838, 2021). "Patients in stage 5 CKD (CKD5) with severe secondary hyperparathyroidism (SHPT) are at increased risk of cardiovascular disease and death due to increased synthesis and secretion of parathyroid hormone (PTH)." (PMID 34044733, 2021). "After all the secondary hyperparathyroidism patients that followed the indication in guidelines received surgery, PTH decrease to 30.06 ± 12.65, 112.46 ± 37.27 and 50.54 ± 15.27 pmol/L in M + S, M and S group (P = 0.01)." (PMID 33933053, 2021). "In the animal study, we provided a high‐calcium diet to limit the possible effect of PTH on the study results, while significant secondary hyperparathyroidism was still detected in the nephrectomized groups." (PMID 32786093, 2021). "On the other hand, high levels of PTH, as in primary and secondary hyperparathyroidism, lead to bone resorption." (PMID 34068220, 2021). "Patients with PTH levels > 200 pg/mL were considered to suffer from clinically significant secondary hyperparathyroidism." (PMID 33921361, 2021). "Persistent FGF 23 is one cause of secondary hyperparathyroidism in CKD as a long-term inducer of parathyroid cell proliferation and PTH secretion." (PMID 35145471, 2021). "We believe that rhGH therapy should be discontinued in patients with persistent severe secondary hyperparathyroidism (PTH >500 pg/ml) and that it can be resumed when PTH levels return to the desired range." (PMID 33013690, 2020). "In the current model of mTAL‐impaired GlatmTg(CAG‐A4GALT) mice with normal CrCl, a decrease in blood Ca2+ led to an elevation in plasma PTH levels and subsequent secondary hyperparathyroidism." (PMID 32617522, 2020). "In contrast, as the prevalence of secondary hyperparathyroidism increases with age, the relationship between PTH levels and lower 25(OH)D levels becomes clearer in older individuals." (PMID 32813765, 2020). "We reported that in mice models of primary and secondary hyperparathyroidism, the presence of SFB in the gut microbiota, and the SFB-dependent expansion of intestinal Th17 cells were sufficient for PTH to stimulate bone resorption and induce bone loss." (PMID 31980603, 2020).
secondary hyperparathyroidism (continued). "Normally, in the presence of inadequate vitamin D status, calcium absorption is lower than optimal and there is a compensatory increase in PTH levels (secondary hyperparathyroidism), with a subsequent stimulation of bone reabsorption and accelerated bone loss." (PMID 33033332, 2020). "One of these patients suffered a secondary hyperparathyroidism with vitamin D value of 4.53 ng/mL and a PTH of 176 pg/mL." (PMID 31991539, 2020). "In patient D, the PTH was 18 pmol/l with normal calcium and vitamin D levels, which points at a secondary hyperparathyroidism possibly due to malabsorption." (PMID 32725291, 2020). "The patient then underwent surgical parathyroidectomy (PTX) for secondary hyperparathyroidism at 43 years of age, which resulted in decreased levels of parathyroid hormone (PTH)." (PMID 33180218, 2020). "Possible ectopic parathyroid hormone (PTH) production in adipose tissues surrounding hyperplastic parathyroid glands was examined in patients with secondary hyperparathyroidism (SHPT)." (PMID 32094398, 2020). "Cancer-derived PTHrP or PTH hypersecreted due to secondary hyperparathyroidism in CKD is responsible for such modifications." (PMID 32751307, 2020). "Four patients (8%) from the control group were diagnosed with secondary hyperparathyroidism; all participants in the diabetes group had PTH values within the reference interval." (PMID 33352890, 2020). "It has been shown that during MIP a greater IOPTH drop was observed 10 minutes after excision in the PTH 3G compared to the PTH 2G assay in both primary and secondary hyperparathyroidism." (PMID 32256573, 2020). "Secondary hyperparathyroidism (SHPT) is a complex disease due to increased parathyroid hormone (PTH) production, which affects the metabolism of calcium and phosphorus and causes further abnormal PTH secretion, usually leading to 4-gland hyperplasia." (PMID 32746794, 2020). "Secondary hyperparathyroidism from over-secretion of parathyroid hormone (PTH) is a common complication in patients with CKD, but there are few studies on PTH and cardiovascular calcification or apoptosis." (PMID 31106631, 2019). "In total (n = 130), 10.4% of participants presented with secondary hyperparathyroidism (PTH concentrations > 6.9 pmol/L)." (PMID 31167443, 2019). "In patients with persistent severe secondary hyperparathyroidism (parathyroid hormone (PTH) >500 pg/ml)." (PMID 31197263, 2019). "Elevated inorganic phosphate levels promote excessive parathyroid hormone secretion, which contributes to the aetiology of secondary hyperparathyroidism." (PMID 31619668, 2019). "GH therapy should be withheld in patients with persistent severe secondary hyperparathyroidism (PTH >500 pg/ml) and can be reinstituted when PTH levels return to the desired target range." (PMID 31197263, 2019). "At this time, secondary hyperparathyroidism with elevated parathyroid hormone and hyperphosphatemia developed and pharmacologic treatment was applied." (PMID 31730449, 2019). "It has been suggested that the mechanism of this phenomenon is related to secondary hyperparathyroidism since the prevention of excess PTH by PTX or the treatment with verapamil (which blocks the effects of PTH) corrected compromised hepatic lipase metabolism." (PMID 31752189, 2019). "Vitamin deficiency was ascertained by attaining low levels of 25(OH)VitD as well as changes in bone turnover biomarkers such as increased PTH signaling (secondary hyperparathyroidism) and alkaline phosphatase activity in blood." (PMID 30609750, 2019). "The median expected PTH in clinical group of secondary hyperparathyroidism at a given age, calcium and 25OHD is lower than the measured iPTH." (PMID 31360455, 2019). "The molecular mechanism linking Pi and PTH secretion is relevant for understanding the etiology of secondary hyperparathyroidism (SHPT)." (PMID 31619668, 2019).
secondary hyperparathyroidism (continued). "Secondary hyperparathyroidism is defined as a PTH two to nine times the upper normal value of the normal values of the healthy population (15–65 or 15–46 pg/mL)." (PMID 31817421, 2019). "The resultant decrease in serum calcium levels stimulates PTH secretion and contributes to the pathogenesis of secondary hyperparathyroidism." (PMID 31637056, 2019). "Loss of active vitamin D subsequently leads to increased parathyroid hormone (PTH) production, so-called secondary hyperparathyroidism, eventually contributing to increased calcium, phosphate, and FGF-23 levels." (PMID 31551803, 2019). "By Spearman rank correlation analysis, we observed a significant correlation between lower 25(OH)D levels and increased PTH concentrations in RA patients (r = 0.3609; P = 0.0063), indicating the presence of secondary hyperparathyroidism." (PMID 31557191, 2019). "It has been demonstrated in the uremic patients with secondary hyperparathyroidism patients that electroencephalography (EEG) changes are corrected upon repression of the serum parathyroid hormone (PTH) by medical or surgical treatment." (PMID 31126169, 2019). "On the other hand, serum PTH level was elevated in aged rats, possibly due to the age-related secondary hyperparathyroidism (p < 0.01 vs. Mature)." (PMID 30564129, 2018). "A diagnosis of secondary hyperparathyroidism, therefore, depends on the measurement of an insufficient or deficient amount of 25-OHD in association with the high levels of PTH." (PMID 30723655, 2018). "The high frequency of secondary hyperparathyroidism in our cohort is consistent with the low average calcium serum levels, relatively high PTH levels and average DPD levels that exceeded the upper reference value." (PMID 30579337, 2018). "Secondary hyperparathyroidism (SHPT) is part of CKD-MBD and characterized by high amounts of parathyroid hormone (PTH) associated with high turnover bone disease and vascular calcification." (PMID 30450134, 2018). "In conclusion, these findings cast doubt on the reliability of available cut-off points for PTH values that are in use or have been proposed to guide therapy for secondary hyperparathyroidism in dialysis patients." (PMID 30524306, 2018). "Moderate (controlled) secondary hyperparathyroidism was defined as PTH between 130 pg/ml and 585 pg/ml (2–9 times the upper limit of normal) and severe (uncontrolled) secondary hyperparathyroidism as PTH > 585 pg/ml (9 times the upper limit of normal)." (PMID 29415666, 2018). "A common consequence of chronic kidney disease is secondary hyperparathyroidism, or excessive serum parathyroid hormone (PTH), which is largely attributed to the retention of phosphate." (PMID 29295646, 2018). "In relation to vitamin D status, elevated PTH (secondary hyperparathyroidism PTH ≥65 ng/L, that is, 6.89 pmol/L) was detected in 55.81%, 31.30% and 27.57% of adolescents with vitamin D severe deficiency, deficiency and insufficiency, respectively." (PMID 30068613, 2018). "The accurate measurement of PTH plays a vital role in the clinical diagnosis, treatment, and prognosis of patients with secondary hyperparathyroidism (SHPT)." (PMID 30627584, 2018). "Dietary phosphorus restriction was not used in the Nx-Control group to compare the mild increase in PTH to severe secondary hyperparathyroidism." (PMID 29394885, 2018). "There are many uremia-associated factors that contribute to bone fragility, including severe secondary hyperparathyroidism, skeletal resistance to parathyroid hormone, and bone mineralization disorders." (PMID 28421193, 2017). "Vitamin D was below the reference range (25-hydroxy vitamin D levels < 30 ng/mL) in 95.1%, and secondary hyperparathyroidism (PTH greater than 65 pg/mL) was found in 69.1% of patients." (PMID 28045952, 2017). "The cutoff value for vitamin D using PTH levels as reference was 14.3 ng/ml which represents the optimum vitamin D levels that prevents secondary hyperparathyroidism among the tested subjects." (PMID 28124221, 2017).
secondary hyperparathyroidism (continued). "Secondary hyperparathyroidism (SHPT) occurs due to a progressive increase in the level of parathyroid hormone (PTH) in diseases that affect the metabolism of calcium or phosphorus and is a common complication in patients with chronic kidney disease." (PMID 29233127, 2017). "Although teriparatide should be used with caution in osteoporotic patients with CKD due to higher blood PTH level in secondary hyperparathyroidism associated with CKD, intermittent PTH administration can be used to induce an anabolic effect on bone in CKD." (PMID 28421193, 2017). "Haemorrhage has also been reported into hyperplastic parathyroid glandular tissue in secondary hyperparathyroidism in patients undergoing haemodialysis and in one patient after suppression of PTH with cinacalcet." (PMID 28637440, 2017). "In the Group A base sample, PTH had shown normal values; secondary hyperparathyroidism was expected as a result of hypovitaminosis D." (PMID 26827062, 2016). "We used data from a prospective cohort of Japanese hemodialysis patients with secondary hyperparathyroidism; the criteria were: intact parathyroid hormone concentrations ≥ 180 pg/mL or use of an intravenous or oral vitamin D receptor activator." (PMID 27764168, 2016). "Secondary hyperparathyroidism, defined as intact PTH greater than 69 pg/mL, was found in 3 of 115 cases (2.61%) of CHB patients, but in none of the controls." (PMID 27399065, 2016). "The likely mechanism behind pseudogout in CKD is secondary hyperparathyroidism, which is due to increased resistance to the parathyroid hormone (PTH)." (PMID 27803833, 2016). "A reduction in serum PTH concentrations is uncharacteristic for feline renal disease—cats with chronic kidney disease are often hypocalcemic and therefore tend to develop secondary hyperparathyroidism and have increased serum PTH." (PMID 27243456, 2016). "In pediatric peritoneal dialysis patients, treatment with calcium carbonate or sevelamer resulted in equivalent control of phosphate, PTH and skeletal changes of secondary hyperparathyroidism." (PMID 27658028, 2016). "Most stage 5 CKD patients have abnormal blood mineral levels and elevated levels of parathyroid hormone (PTH), a condition known as secondary hyperparathyroidism (SHPT)." (PMID 26122041, 2015). "Secondary hyperparathyroidism (SHPT) is managed primarily via clinical control of the biochemical parameters parathyroid hormone (PTH), calcium, and phosphorus." (PMID 25886282, 2015). "It is important to note that the HERO Study excluded patients with a serum parathyroid hormone level greater than 100 pmol/L, such that included patients only had mild-to-moderate secondary hyperparathyroidism." (PMID 26284153, 2015). "Secondary hyperparathyroidism characterized by increased secretion of PTH, is one of the major serious complications of patients with chronic renal failure on long-term hemodialysis." (PMID 26058796, 2015). "Low serum calcitriol belongs to main stimulators for PTH production and triggers the initial as well as advanced forms of secondary hyperparathyroidism." (PMID 26064917, 2015). "Effect modifications by the severity of secondary hyperparathyroidism (intact parathyroid hormone [iPTH] level), sex, and systolic blood pressure were also examined." (PMID 25874620, 2015). "Secondary hyperparathyroidism is determined by high PTH levels, normal to low calcium levels and concurrent decrease in vitamin D levels." (PMID 26010883, 2015). "Secondary hyperparathyroidism was generally (where reported) determined according to dialysis status, high PTH levels but low/normal calcium levels, and serum creatinine or drugs influencing levels of calcium (e.g. vitamin D analogs)." (PMID 26010883, 2015). "We arbitrarily defined primary hyperparathyroidism as albumin-corrected total serum calcium ≥9.5 mg/dL (unsuppressed serum calcium with an elevated PTH level, n = 212), and secondary hyperparathyroidism as calcium <9.5 mg/dL (n = 237)." (PMID 25514572, 2014).
secondary hyperparathyroidism (continued). "Primary hyperparathyroidism, familial hypocalciuric hypercalcemia, familial hyperparathyroidism, and secondary hyperparathyroidism are PTH mediated." (PMID 24716007, 2014). "Eight patients with an estimated glomerular filtration rate between 15 and 44 mL/min/1.73 m2 and an intact parathyroid hormone (PTH) level higher than 110 pg/mL received oral paricalcitol (1 μg/48 hours) as therapy for secondary hyperparathyroidism." (PMID 24511210, 2014). "This analog has a short effect on bone and intestine, tissues responsible for calcium homeostasis, and a longer effect on PTH levels, making this analog ideal for the treatment of secondary hyperparathyroidism." (PMID 24772087, 2014). "Biochemical evidences of suboptimal bone health are elevated alkaline phosphatase (ALP) and elevated PTH levels (secondary hyperparathyroidism or SHPT)." (PMID 24566435, 2014). "In our series PTH levels were significantly related to seasons, with a winter-time prevalence of secondary hyperparathyroidism three times higher than the prevalence during summer." (PMID 24902694, 2014). "The decrease in plasma PTH concentrations is somewhat atypical for Cushing's syndrome because patients with this frequently have secondary hyperparathyroidism." (PMID 24302625, 2014). "Primary hyperparathyroidism (PHPT), familial hypocalciuric hypercalcemia, familial hyperparathyroidism, and secondary hyperparathyroidism are PTH mediated." (PMID 24716007, 2014). "Biochemical evidences of suboptimal bone health are: elevated alkaline phosphatase, a surrogate marker for increased bone turnover, and elevated PTH levels (secondary hyperparathyroidism or SHPT)." (PMID 24566435, 2014). "Reduced activation of the vitamin D receptor in CKD, leading to increased expression of PTH and growth of the parathyroid glands, plays a critical role in the pathogenesis of secondary hyperparathyroidism." (PMID 24511210, 2014). "It is proffered that there is a contradictory relation between serum level of vitamin C and parathyroid hormone (PTH) in hemodialysis patients with secondary hyperparathyroidism." (PMID 24693502, 2013). "The goal of this study was to assess the effects of the supplemental vitamin C on parathyroid hormone among hemodialysis patients with secondary hyperparathyroidism." (PMID 24693502, 2013). "Chronic kidney disease (CKD) patients experience many health issues including mineral and bone disorders and secondary hyperparathyroidism (SHPT) with elevated parathyroid hormone (PTH)." (PMID 24303131, 2013). "Two patients (4.4%) had normal levels of vitamin D. Among patients with decreased vitamin D, 13 (28.2%) had secondary hyperparathyroidism with PTH levels between 70 pg/mL and 217 pg/mL." (PMID 27398385, 2013). "Despite the generally low levels of serum 25OHD, only 8 patients (3.7%) had clear evidence of secondary hyperparathyroidism (PTH > 55 pg/mL)." (PMID 23724340, 2013). "Calcimimetic CSR blocker (cinacalcet) has also been introduced in recent years (FDA-approved in March, 2004) for treating severe (PTH > 600 pg/mL) secondary hyperparathyroidism." (PMID 23760058, 2013). "The high Pi together with low Ca2+ and 1,25(OH)2D3 levels are known to stimulate secretion of parathyroid hormone (PTH), with secondary hyperparathyroidism; the accumulating PTH stimulating osteoclastic activity." (PMID 24303178, 2013). "In our cohort, only 8 patients (3.7%) had vitamin D levels <30 ng/mL with clear evidence of secondary hyperparathyroidism based on the laboratory normal range (PTH > 55 pg/mL)." (PMID 23724340, 2013). "This study was performed to evaluate the vitamin C effects on parathyroid hormone among hemodialysis patients with secondary hyperparathyroidism." (PMID 24693502, 2013). "Secondary hyperparathyroidism (serum PTH ≥ 65 pg/mL) was observed in 13.79% of the subjects (IC 95%, 13.79%–24.74%)." (PMID 24304609, 2013).